EMP3 (epithelial membrane protein 3 (MAM blood group))
Diseases named in the same sentence as EMP3 in open-access papers (continued):
Sharing a sentence is not in itself a finding about the gene and the disease.
esophageal cancer (2 papers, 2019 to 2021). A primary or metastatic malignant neoplasm involving the esophagus. "The survival rate of patients with esophageal cancer after recurrence is significantly lower in patients with low levels of EMP3." (PMID 31652725, 2019). "The overexpression of EMP3 in esophageal cancer cells inhibits their growth and facilitates their death." (PMID 31652725, 2019). "The expression levels of EMP3 and telomerase reverse transcriptase inversely correlate in several esophageal cancer cell lines and tissue samples." (PMID 31652725, 2019).
oligodendroglial tumor (2 papers, 2013 to 2015). Oligodendrogliomas are cerebral tumors that are differentiated from other gliomas on the basis of their unique genetic characteristics and better response to chemotherapy. "The unexpected association of the EMP3 hypermethylation with longer OS in the 64 patients with oligodendroglial tumors by univariate analysis is in agreement with a previous observation." (PMID 24083241, 2013). "In oligodendroglial tumors, the EMP3 gene was hypermethylated in 33 of 42 WHO grade II tumors (78.6%) and in 13 of 31 WHO grade III tumors (41.9%)." (PMID 24083241, 2013). "The correlation of EMP3 promoter hypermethylation on patient survival was evaluated in 64 oligodendroglial tumors (38 WHO grade II and 26 WHO grade III) and in 60 GBMs." (PMID 24083241, 2013). "EMP3 promoter hypermethylation is significantly associated with IDH1/IDH2 mutations in both astrocytic and oligodendroglial tumors." (PMID 24083241, 2013). "The EMP3 promoter hypermethylation correlates with statistical significance with better OS in patients with oligodendroglial tumors." (PMID 24083241, 2013). "A favorable prognostic significance on overall survival of the EMP3 promoter hypermethylation was found in patients with oligodendroglial tumors." (PMID 24083241, 2013). "EMP3 promoter hypermethylation is prevalent in oligodendroglial tumors (63%) and in oligoastrocytomas (70%) upon astrocytic tumors (18%), as already reported." (PMID 24083241, 2013). "Our observations support EMP3 promoter hypermethylation as an early epigenetic event in gliomagenesis, in both astrocytic and oligodendroglial tumors." (PMID 24083241, 2013). "Multivariate analysis by Cox's proportional hazard regression model in oligodendroglial tumors identified total 1p/19 codeletion as the main independent prognostic factor (P < 0.0001), followed by the histologic tumor grade (P = 0.001) and the EMP3 promoter hypermethylation (P = 0.071)." (PMID 24083241, 2013). "After patient stratification for the histologic tumor grade in astrocytic and oligodendroglial tumors, the EMP3 promoter hypermethylation was significantly more frequent in WHO grade II (45 of 63, 71.4%) than in WHO grade III tumors (21 of 47, 44.7%) (P = 0.0001)." (PMID 24083241, 2013). "Patient stratification for the histological type revealed that EMP3 promoter hypermethylation was significantly associated with IDH1/IDH2 mutations in astrocytic tumors (P = 0.0088), GBMs included (P = 0.0012), in oligodendroglial tumors (P = 0.0006), and in oligoastrocytomas (P = 0.0095)." (PMID 24083241, 2013). "In the literature, the EMP3 hypermethylation has been found to be significantly associated with lower transcript levels in both astrocytic and oligodendroglial tumors, with one exception for the latter, suggesting in these tumors the existence of alternative EMP3 epigenetic mechanisms." (PMID 24083241, 2013). "However, 83.3% of oligodendroglial tumors with both total 1p/19q codeletion and EMP3 promoter hypermethylation did not display EMP3 protein expression, as detected by IHC or WB." (PMID 24083241, 2013).
phyllodes tumor (2 papers, 2020 to 2023). A benign, borderline, or malignant fibroepithelial neoplasm arising from the breast and rarely the prostate gland. "With increasing histologic grade, the expression of EMP1, EMP2, and EMP3 decreases in the epithelial component and increases in the stromal component of phyllodes tumors." (PMID 37008256, 2023). "Univariate analysis of the impact of EMP1, EMP2, and EMP3 expression in phyllodes tumors." (PMID 32857809, 2020).
sarcoma (2 papers, 2023 to 2026). A usually aggressive malignant neoplasm of the soft tissue or bone. "Further analysis of differentially methylated regions between tumors within the novel group and CIC-rearranged sarcoma showed aberrant methylation patterns, including promoter region hypomethylation amongst others of CD44, EMP3, and VIM in these tumors." (PMID 36964296, 2023). "High expression of CD44, EMP3 and VIM may be useful to distinguish the tumors from CIC-rearranged sarcoma." (PMID 36964296, 2023).
astrocytic tumor (1 paper, 2013). A glial tumor of the brain or spinal cord showing astrocytic differentiation.
calcification (1 paper, 2024). Process by which organic tissue becomes hardened by the physiologic deposit of calcium salts. "Moreover, skeletal and cardiac muscles of D2-mdx mice exhibit calcifications, due to the presence of the Dyscalc loci in the ATP Binding Cassette Subfamily C Member 6—ABCC6 and Epithelial Membrane Protein 3—EMP3 genes." (PMID 39535998, 2024).
endometrial cancer (1 paper, 2019). Primary or metastatic malignant neoplasm involving the endometrium (mucous membrane that lines the endometrial cavity). "EMP3 may be associated with estrogen receptor α-mediated signaling pathways during the development of endometrial cancer." (PMID 31652725, 2019). "Recent bioinformatics analysis indicates that EMP3 contributes to the pathogenesis of endometrial cancer." (PMID 31652725, 2019).
leishmaniasis (1 paper, 2023). Infectious disease that is transmitted through the bite of hematophagous female phlebotomine sand flies. "The KEGG enrichment analysis showed that EMP3 was significantly correlated with viral myocarditis and leishmaniasis." (PMID 37887529, 2023).
leukemia (1 paper, 2023). A malignant (clonal) hematologic disorder, involving hematopoietic stem cells and characterized by the presence of primitive or atypical myeloid or lymphoid cells in the bone marrow and the blood. "By performing network analysis based on physical interactions and co-expression, we demonstrated that the upregulated genes LGALS1, S100A10, EMP3, and S100A4 in the residual leukemia-like cells were involved in a functional module with LGALS1 as a hub gene." (PMID 36543880, 2023).
oral squamous cell carcinoma (1 paper, 2022). "The reduction of EMP3 can reduce the ability of oral squamous cell carcinoma cells to migrate." (PMID 36217151, 2022). "In oral squamous cell carcinoma, miR-765 might be involved in regulating EMP3." (PMID 36217151, 2022).
pilocytic astrocytoma (1 paper, 2013). Pilocytic astrocytoma is a rare subtype of low-grade glioma of the central nervous system characterized by a well circumscribed, often cystic, brain tumor with a discrete mural nodule and long, hair-like projections that extend from the neoplastic astrocytes. "In pilocytic astrocytomas, EMP3 promoter hypermethylation is rather rare." (PMID 24083241, 2013).
Stroke (1 paper, 2012). Sudden impairment of blood flow to a part of the brain due to occlusion or rupture of an artery to the brain. "New stroke-genes involved presumably in extracellular matrix remodelling included the transiently upregulated carboxipeptidase-encoding Cpxm1 and the permanently upregulated epithelial membrane protein 3 (Emp3)." (PMID 23251410, 2012).
triple-negative breast carcinoma (1 paper, 2021). An invasive breast carcinoma which is negative for expression of estrogen receptor (ER), progesterone receptor (PR), and human epidermal growth factor receptor 2 (HER2). "Consistent with the fact that RAD51AP1 functions in both luminal ER-positive and triple-negative breast cancers, EMP3 affects RAD51 expression as well as DNA replication, DNA damage repair, and stem-like properties in both ER-positive MCF7 and triple-negative MDA-MB-231/HS578 cells." (PMID 34511602, 2021).
tumor (57 papers, 2005 to 2026). "Among these, EMP3 was found as the top signature-associated gene, yet its roles in tumor biology are poorly reported." (PMID 41225146, 2025). "EMP3 is a member of the peripheral myelin protein 22-kDa (PMP22) gene family, and it is demonstrated that reintroduction in EMP3-deficient cancer cells inhibits colony formation and tumor growth in xenografts." (PMID 35646656, 2022). "In this study, we identified EMP3 as a potential tumor-associated gene that is highly expressed in CD44-high primary GBM." (PMID 27527869, 2017). "A study by Alaminos M showed that EMP3 reintroduction in EMP3-deficient cancer cells inhibits colony formation and tumor growth in xenografts, indicating a tumor suppressing function of the EMP3 gene." (PMID 27801851, 2016). "In addition, EMP3 is an important immunosuppressive factor for recruiting tumor-associated macrophages in GBM, which induces suppression of T-cell infiltration and leads to tumor progression." (PMID 38019838, 2023). "As stromal EMP3 expression showed increased expression along with the histologic grade as well as was intimately associated with tumor aggressiveness and prognosis in the present study, it might be considered as a good candidate for treatment." (PMID 32857809, 2020). "EMP3 is a robust mesenchymal-associated biomarker linked to EMT, tumor progression, and clinical outcomes in USs, supporting its potential utility as a prognostic indicator and therapeutic target." (PMID 41977488, 2026). "In contrast, EMP1 and EMP3 expression levels in the Tumor group were only marginally higher than those in the Normal group, and these differences were not statistically significant (p > 0.05)." (PMID 39866225, 2025). "Functional experiments showed that the knockdown of EMP3 significantly suppressed the malignant phenotype of tumor cells in terms of proliferation and migration." (PMID 38229014, 2024). "Elevated EMP3 in GBM areas was accompanied by high expression of PD-L1 and abundant M2 Tumor-Associated Macrophage (TAM) recruitment but a lake of T cell infiltration." (PMID 38229014, 2024). "By sustaining EGFR/CDK2 activity and by being expressed at such high levels in this tumor entity, EMP3 provides an additional level of resistance that protects tumor cells from targeted kinase inhibitors." (PMID 37936247, 2023). "Patients with tumor cells with low EMP3 and CHI3L1 expression levels had a better prognosis than patients with tumor cells with high EMP3 and CHI3L1 expression levels." (PMID 37887529, 2023). "In recent years, abnormal expression of EMP3 has been observed in many cancers, and many studies have focused on EMP3 in tumor progression and malignant transformation." (PMID 37887529, 2023). "EMP3 can promote tumor growth along with activation of TGF-β signaling in intracranial GBM xenografts." (PMID 35647198, 2022). "Evidence has shown that EMP3 is a candidate tumor suppressor gene for some solid tumors, such as nervous system tumors, which can significantly inhibit the proliferation of tumor cells." (PMID 36217151, 2022). "Exogenous expression of the EMP3 gene has been found to limit tumor cell proliferation and act as a tumor suppressor gene." (PMID 35982458, 2022). "There are some evidences that the high EMP3 expression in GBM is accompanied by high PD-L1 expression and infiltration of tumor-associated macrophages (TAM)." (PMID 36217151, 2022). "EMP3 also plays a putative tumor-suppressing role in esophageal squamous cell carcinoma and gallbladder cancer." (PMID 34511602, 2021). "In upper urinary tract urothelial carcinoma, EMP3 enhances tumor progression the ErbB2‐PI3K‐AKT signaling pathway." (PMID 34268874, 2021). "Recently, many studies have focused on the role of EMP3 in tumor progression and malignant transformation." (PMID 34268874, 2021). "In combination with prognosis analysis, this finding shows that EMP3 functions as a suppressor of tumor growth in this type of cancer." (PMID 34511602, 2021).
tumor (continued). "Epithelial membrane protein 3 (EMP3) is considered to be a tumor suppressor, but this article found that this gene is a prognostic risk gene for LGG." (PMID 34295296, 2021). "After elucidating the correlation between EMP3 expression and tumor malignancy, we aimed to demonstrate the prognostic value of EMP3." (PMID 34268874, 2021). "Above novel prognostic factors tend to facilitate tumor progression per se; however, the protumor and immunomodulatory effects of EMP3 were both demonstrated previously." (PMID 34268874, 2021). "Using an EMP3-binding PROTAC, EMP3 can potentially be marked for proteasomal degradation with ubiquitin, and the tumor cells’ own proteasome degrades it thereafter." (PMID 34067658, 2021). "As is shown in the heatmap, with an increase in EMP3 expression, the tumor microenvironment is more likely to present respond to immune checkpoint blockades (ICBs)." (PMID 34268874, 2021). "In NSCLC, EMP1 was associated with clinical resistance of gefitinib, EMP2 gene silencing resulted in activation of ERK and JNK in NSCLC cells, and EMP3 expression was significantly lower in tumor tissues compared to healthy lung tissues." (PMID 33799364, 2021). "We observed that knockout of EMP3 in GL261 cells suppressed tumour growth and prolonged mouse survival." (PMID 33964937, 2021). "Histologically, cells with high EMP3 expression were found to be especially frequent within the tumor core." (PMID 34067658, 2021). "Detailed information on baseline characteristics, tumor malignancy, comprehensive histopathological biomarkers, and EMP3 expression levels is summarized." (PMID 34268874, 2021). "In line with other findings, EMP3 knockdown in HCC cells reduced cell proliferation and attenuated tumor growth in vivo, while EMP3 overexpression in TSGH8301 cells promoted cell growth and increased the proportion of Ki-67-positive cells in vitro." (PMID 34067658, 2021). "The function of EMP3 currently still lacks definition; EMP3 has been reported as both a tumour suppressor gene and an oncogene in studies of cancers from diverse tissues." (PMID 32678083, 2020). "EMP3 has been reported as a tumour suppressor gene in various solid tumours and as a possible therapeutic target in cancer." (PMID 32678083, 2020). "We show that EMP3, a purported tumour suppressor in various solid tumours, is expressed in erythroid cells." (PMID 32678083, 2020). "In LGG tumor tissues, EMP3, IGFBP2, TIMP1 and SERPINE1 are all highly expressed, compared with normal brain tissues." (PMID 32328202, 2020). "The EMP3 levels in the tumor inversely correlate with the Ki67 expression, suggesting increased cell proliferation in the absence of EMP3 in malignant tumors." (PMID 31652725, 2019). "The inoculation of EMP3-depleted GBM cells in nude mice showed smaller tumor formation than that of EMP3-overexpressed cells." (PMID 31652725, 2019). "The expression of caspase-3, a marker of apoptosis, is upregulated in the tumor lysates derived from EMP3-depleted cells." (PMID 31652725, 2019). "Therefore, EMP3 might be a tumor-associated gene involved in GBM progression." (PMID 27527869, 2017). "Our results indicated that EMP3 depletion suppressed tumor growth and induced apoptosis in murine xenograft models." (PMID 27527869, 2017). "In the present study, we demonstrated the potential roles of EMP3 in tumor aggressiveness of HCC cells, and found that EMP3 was highly expressed in the tumorous tissues comparing to non-tumorous tissues of HCC patients." (PMID 26472188, 2015). "Activation of the PI3K/Akt pathway by EMP-1 in NSCLC cells or by EMP-3 in HCC cells in the current study promoted tumor aggressiveness." (PMID 26472188, 2015). "The in vivo tumor growth of HCC was effectively suppressed by knockdown of EMP3 in a xenograft mouse model." (PMID 26472188, 2015). "In our study, we found that knockdown of EMP3 suppresses cell proliferation, cell cycle progression, migration, invasion, and tumor growth of HCC cells." (PMID 26472188, 2015).